LRCH1 (leucine rich repeats and calponin homology domain containing 1)
Description:
Acts as a negative regulator of GTPase CDC42 by sequestering CDC42-guanine exchange factor DOCK8. Probably by preventing CDC42 activation, negatively regulates CD4(+) T-cell migration.
Synonyms: NP81; CHDC1; KIAA1016
Tractability: PROTAC: ubiquitination databases record sites on it; its protein half-life has been measured.
Gene: Protein-coding gene on chromosome 13 (46,553,168 to 46,753,040, forward strand). Ensembl gene ENSG00000136141.
Subcellular location: Cytoplasm
Subcellular location (Human Protein Atlas): Actin filaments; Cytosol; Nucleoli
Gene Ontology:
Molecular function: protein binding
Biological process: cellular response to chemokine; negative regulation of GTPase activity; negative regulation of T cell migration
Cellular component: cytoplasm
Genetic constraint (gnomAD): Loss-of-function variants: 17 observed, 53.35 expected, observed/expected ratio (o/e) 0.32, 90% interval 0.22 to 0.48. The upper end of that interval is the gene's LOEUF score, 0.48, which puts it in group 2 of 6, group 1 being the genes least tolerant of losing a copy. Missense variants: 598 observed, 736.13 expected, observed/expected ratio (o/e) 0.81, 90% interval 0.76 to 0.87. Synonymous variants: 294 observed, 285.7 expected, observed/expected ratio (o/e) 1.03, 90% interval 0.94 to 1.13.
Homologues: Orthologues: macaque LRCH1 (99% identical), chimpanzee LRCH1 (99% identical), pig LRCH1 (90% identical), rat Lrch1 (87% identical), dog LRCH1 (78% identical), mouse Lrch1 (76% identical), rabbit LRCH1 (73% identical), guinea pig LRCH1 (69% identical), tropical clawed frog lrch1 (58% identical), zebrafish lrch1 (52% identical). Paralogues in human: LRCH2 (43% identical), LRCH3 (41% identical), LRCH4 (36% identical), LRRK1 (24% identical), SCRIB (17% identical), LRRC7 (16% identical), PHLPP1 (16% identical), ERBIN (16% identical), PHLPP2 (15% identical), PIDD1 (13% identical), MFHAS1 (13% identical), LRRC28 (11% identical), and 19 more.
Diseases named in the same sentence as LRCH1 in open-access papers:
LRCH1 is named in the same sentence as 22 diseases in open-access papers, as found by Europe PMC text mining. Sharing a sentence is not in itself a finding about the gene and the disease. The quoted sentences say what the papers report.
knee osteoarthritis (3 papers, 2015 to 2024). "Lrch1 was found in a previous GWAS exploring the knee osteoarthritis phenotype in humans, but large-scale replication studies then dismissed it from being casual." (PMID 26611327, 2015).
Stroke (3 papers, 2019 to 2025). Sudden impairment of blood flow to a part of the brain due to occlusion or rupture of an artery to the brain. "This suggested that LRCH1 was strongly associated with cardiac mechanisms of stroke, such as large-artery atherosclerotic stroke, cardioembolic stroke, and small-vessel stroke." (PMID 31392102, 2019). "Besides, two genes (SLC25A44 and LRCH1), whose expression were significantly associated with stroke after Bonferroni correction, were identified as candidate genes in a recent TWAS in adipose." (PMID 35449099, 2022). "SLC25A44 and LRCH1 were the only two genes passing the Bonferroni correction threshold (P < 0.05/11,826) for all gene-stroke features, which implied that they were strongly associated with stroke." (PMID 31392102, 2019). "LRCH1 was also recognized as a risk gene for stroke in the GWAS included in our study." (PMID 31392102, 2019). "Our study also showed that depressed expression of LRCH1 was associated with stroke." (PMID 31392102, 2019). "The TWAS identified 515 transcriptome-wide significant tissue-specific genes, among which SLC25A44 (P = 5.46E−10) and LRCH1 (P = 1.54E−6) were significant by Bonferroni test for stroke." (PMID 31392102, 2019). "Our TWAS identified two genes, i.e., SLC25A44 and LRCH1, that were significant for stroke after Bonferroni correction." (PMID 31392102, 2019). "Thus, LRCH1 might act a role in interfering T cell migration in stroke." (PMID 31392102, 2019).
ulcerative colitis (3 papers, 2020 to 2023). An inflammatory bowel disease involving the mucosal surface of the large intestine and rectum. "In the colonic mucosa of ulcerative colitis patients, LRCH1 expression is markedly decreased and disease severity more pronounced with lower levels of LRCH1 expression." (PMID 33072765, 2020). "Here, CD4+ T cells mediate the pathogenesis of ulcerative colitis and massively infiltrate into the colonic mucosa, potentially by a mechanism negatively regulated by LRCH1 as migration of CD4+ T cells from ulcerative colitis patients is reduced by LRCH1 overexpression." (PMID 33072765, 2020). "Low LRCH1 levels, which increase migration of CD4+ T cells, have also been found in patients with ulcerative colitis." (PMID 37365285, 2023).
osteoarthritis (2 papers, 2019 to 2020). A noninflammatory degenerative joint disease occurring chiefly in older persons, characterized by degeneration of the articular cartilage, hypertrophy of bone at the margins and changes in the synovial membrane. "So far, increased studies have reported that LRCH1 gene polymorphisms are associated with osteoarthritis." (PMID 31842790, 2019). "Previous studies have demonstrated that LRCH1 participated in the pathogenesis of several immune diseases (e.g., osteoarthritis), however, the roles of LRCH1 in UC are still obscure." (PMID 32210709, 2020). "Considering that the pathogenesis of osteoarthritis and DEACMP are both involved in immunologic mechanisms, these findings imply that LRCH1 might also be associated with the occurrence of DEACMP through its participation in immunologic mechanisms." (PMID 31842790, 2019). "Multiple SNP sites of LRCH1 are connected with osteoarthritis (OA)." (PMID 31842790, 2019).
atherosclerosis (1 paper, 2020). A disease characterized by the build-up of fatty material and calcium deposition in the arterial wall resulting in partial or complete occlusion of the arterial lumen. "A previous study indicates that LRCH1 is upregulated in foam cells by nearly 3-folds in a murine atherosclerosis model, suggesting that perhaps LRCH1 also influence macrophage polarization and function, since foam cells are fat-laden M2 macrophages." (PMID 32631435, 2020).
autoimmune disease (1 paper, 2020). A disorder resulting from loss of function or tissue destruction of an organ or multiple organs, arising from humoral or cellular immune responses of the individual to their own tissue constituents. "Overexpression of LRCH1 or its DOCK8-binding domain (LRR1–9) reduces infiltration of the central nervous system by LRCH1-overexpressing CD4+ T cells in a model of experimental autoimmune disease (EAE)." (PMID 33072765, 2020).
colorectal cancer (1 paper, 2023). A primary or metastatic malignant neoplasm that affects the colon or rectum. "joint test, we identified that the association between diabetes and colorectal cancer risk is modified by a locus on chromosome 13q14.13 within the LRCH1 gene, with genetic variant rs9526201 showing the most significant effect (p-value: 7.84 × 10−09)." (PMID 37365285, 2023). "We also observed that the association of diabetes with colorectal cancer risk was modified by genetic variants located in LRCH1. eQTL as well as gene-expression analysis for the variantxdiabetes interaction suggests that LRCH1 might represent the target gene regulating expression and transcription." (PMID 37365285, 2023). "In this large genome-wide GxE interaction analysis involving more than 30,000 colorectal cancer cases, we found that the association of diabetes status with colorectal cancer was modified by common genetic variants located within the SLC30A8 and LRCH1 genes." (PMID 37365285, 2023).
dementia (1 paper, 2024). Loss of intellectual abilities interfering with an individual's social and occupational functions. "Other correlations within the top 10 most significant include PLEKHH3, RGS14, LRCH1, and PCDHB10, notable for their prior implication in dementia and aging." (PMID 38469573, 2024).
diabetes (1 paper, 2023). "We found a suggestive interaction (P-value: 0.02) of variant rs9534444 (LD R2: 0.52 with rs9526201) with diabetes in relation to LRCH1 gene expression." (PMID 37365285, 2023).
experimental autoimmune encephalomyelitis (1 paper, 2020). An autoimmune demyelinating disease of the central nervous system that is produced experimentally in animals by the injection of homogenized brain or spinal cord in Freund's adjuvant. "A recent study indicates that LRCH1 act to restrain PKCα-DOCK8-Cdc42 module-mediated T cell migration in experimental autoimmune encephalomyelitis, through competing with Cdc42 for interaction with DOCK8." (PMID 32631435, 2020). "It was recently reported that LRCH1 competes with Cdc42 for interaction with DOCK8 and restrains T cell migration in experimental autoimmune encephalomyelitis." (PMID 32631435, 2020).
influenza (1 paper, 2020). An acute viral infection of the respiratory tract, occurring in isolated cases, in epidemics, or in pandemics; it is caused by serologically different strains of viruses (influenzaviruses) designated A, B, and C, has a 3-day incubation period, and usually lasts for 3 to 10 days. "Hence, LRCH1-deficient mice show improved clearance of infection with influenza and L. monocytogenes compared to WT mice and LRCH1-deficient cytotoxic T cells clear B16-MO5 tumor cells more efficiently than WT cells." (PMID 33072765, 2020).
tumor (1 paper, 2020). "LRCH1-deficient NK92 cells show a higher cytotoxicity toward tumor cells, a higher secretion of interferon-γ, TNFα, IL-2 and higher granzyme B levels." (PMID 33072765, 2020). "In LRCH1-deficient NK92 cells phosphorylation of these SFKs is increased at basal levels and further increases in presence of tumor cells compared to control cells." (PMID 33072765, 2020).
LRCH1 also shares sentences with these, for which no sentence is quoted: cancer (2 papers); carbon monoxide poisoning (1); cardioembolic stroke (1); colon tumor (1); immune diseases (1); infection (1); melanoma (1); melanosis (1); psychiatric disorder (1); small vessel stroke (1).